C22orf15 (chromosome 22 open reading frame 15)
Synonyms: FLJ36561; N27C7-3
Tractability: Antibody: the Human Protein Atlas places it where antibodies can reach.
Gene: Protein-coding gene on chromosome 22 (23,762,990 to 23,765,863, forward strand). Ensembl gene ENSG00000169314.
Subcellular location (Human Protein Atlas): Endoplasmic reticulum; Plasma membrane
Genetic constraint (gnomAD): Loss-of-function variants: 21 observed, 20.67 expected, observed/expected ratio (o/e) 1.02, 90% interval 0.72 to 1.46. The upper end of that interval is the gene's LOEUF score, 1.46, which puts it in group 6 of 6, group 1 being the genes least tolerant of losing a copy. Missense variants: 170 observed, 199.68 expected, observed/expected ratio (o/e) 0.85, 90% interval 0.75 to 0.97. Synonymous variants: 78 observed, 80.01 expected, observed/expected ratio (o/e) 0.97, 90% interval 0.81 to 1.18.
Homologues: Orthologues: pig C22orf15 (66% identical), dog C26H22orf15 (64% identical), chimpanzee C22H22orf15 (63% identical), macaque C10H22orf15 (60% identical), mouse Gm867 (57% identical), rat C20h22orf15 (57% identical), tropical clawed frog C22orf15 (32% identical).